FDX1 (ferredoxin 1)
Diseases named in the same sentence as FDX1 in open-access papers (continued):
Sharing a sentence is not in itself a finding about the gene and the disease.
tumor (continued). "Further studies found that knockout of FDX1 neither inhibited the growth of tumor cells nor induced apoptosis or abnormal cell cycle distribution." (PMID 36338763, 2022). "Single-cell RNA sequencing of HCC samples indicated that FDX1 can be detected in both tumor cells and non-tumor cells like fibroblasts and monocytes, but its expression was predominantly detected in hepatic progenitor cells and malignant cells." (PMID 35898502, 2022). "In ACC, COAD, LIHC and STAD, the relative consistent negative correlation of FDX1 and immune checkpoints and tumor infiltrating cells indicated the negative regulating function of FDX1 in these tumors." (PMID 36226187, 2022). "Immunohistochemical results showed that in 5 pairs of ccRCC tissues, FDX1 was positive in tumor-adjacent tissues while negative in tumor tissues." (PMID 36105937, 2022). "Our results suggest that FDX1 may serve as a therapeutic target for various cancers and plays a vital role in tumor immunity by influencing MSI, TMB, and tumor-infiltrating immune cells." (PMID 36210836, 2022). "However, ferredoxin 1 (FDX1), the core regulatory gene in cuproptosis, is rarely studied, and the regulation of FDX1 in tumor biology remains obscure." (PMID 36605188, 2022). "All results showed that the FDX1 in adjacent nontumor tissues was significantly higher than that in tumor tissues." (PMID 36105937, 2022). "Our research first analyzed TCGA database and found that the expression of cuprotosis-related gene FDX1 in adjacent nontumor tissues was higher than that in tumor tissues." (PMID 36105937, 2022). "The other five CRGs, including FDX1, SLC31A1, LIPT2, PDHA1 and GCSH, did not have any mutations in tumor samples." (PMID 36479114, 2022). "Although FDX1 expression (P-value = 0.157) was not decreased statistically significant in HCC tumor tissues, the trend of FDX1 expression was still declined by paired differential analysis." (PMID 36313717, 2022). "For example, knockdown of FDX1 neither inhibited tumor cell growth nor induced apoptosis but inhibited the ATP production and fatty acid oxidation in LUAD cells." (PMID 36210836, 2022). "Among these genes, we focused on the FDX1 gene, and we found that knockdown of FDX1 neither inhibited tumor cell growth nor did it induce apoptosis or abnormal cell cycle distribution." (PMID 34690780, 2021). "Additionally, a set of genes, including AFM, DYNLRB2, FDX1, and SHBG, were significantly downregulated in HCC-R tumor tissues with fold changes ≥4 involved in various small molecule biochemistry and molecular transport mechanisms." (PMID 24377043, 2013). "In a 4T-1 tumor-bearing BALB/c mouse model, comprehensive evaluation of targeting efficiency, antitumor efficacy, and mechanisms of action was conducted via in vivo imaging, tumor volume monitoring, immunohistochemistry (detecting FDX1 and DLAT proteins), and TUNEL staining." (PMID 41599733, 2026). "Thus, we speculated that cuproptosis-related gene FDX1 may affect TCA cycle to retard EMT progress, thereby suppressing the tumor growth and progression of CRC." (PMID 38520567, 2025). "Although, the overall tumor penetrance in Fdx1+/- +/-not significantly altered as compared to WT mice, we indeed observed increased incidences of adenocarcinomas in these mice, which would signal the role of Fdx1-mediated lipid homeostasis in regulation of oncogenesis and warrants further studies." (PMID 38251655, 2024). "No differential expression of FDX1 in other tumor’s stage including ACC, BLCA, BRCA, CESC, etc.." (PMID 36825202, 2023). "In the results of a study, we saw a correlation between FDX1 expression and infiltration of B cells, CD4T cells, CD8T cells, neutrophils, macrophages and dendritic cells (DCs) in a variety of cancers, suggesting a potential role in the tumor immune microenvironment." (PMID 37405988, 2023). "FDX1 was upregulated in tumor tissue as opposed to normal brain tissue (p <0.001)." (PMID 37301546, 2023).
tumor (continued). "Moreover, further analysis was made to investigate the mRNA expression level of CRGs between normal and CRC samples, and we found that the expressions of FDX1, DLD, DLAT, PDHB, and MTF1 were significantly decreased, whereas LIPT1, GLS, and CDKN2A were significantly upregulated in tumor samples." (PMID 37006250, 2023). "FDX1, LIAS, LIPTQ, SLC31A1, and PDHB showed no mutation in LUAD tumor tissues." (PMID 36983664, 2023). "In addition, the expression level of FDX1 in adjacent nontumor tissues was significantly higher than in tumor tissues (P < 0.05)." (PMID 36105937, 2022). "The stemness analysis indicated that a high FDX1 expression in ACC, COAD, and KIRP was correlated with high cancer stemness, which may account for the differences in the prognostic value among various tumor types." (PMID 36605188, 2022). "However, in the pooled survival analysis of all tumor types, although the survival curves were separated, there was no statistical significance between FDX1 altered group and the unaltered group (p > 0.05)." (PMID 36226187, 2022). "Therefore, increasing the expression of FDX1 and DBT could be a potential approach for killing tumor cells in KIRC." (PMID 36338990, 2022). "Furthermore, normal liver tissues did not reveal FDX1 staining, while tumor liver tissues showed moderate staining." (PMID 36210836, 2022). "Therefore, we hypothesised that FDX1 may be involved in regulating tumour progression through metabolic pathways rather than the surrounding immune microenvironment." (PMID 38393693, 2024). "Moreover, high expression of FDX1 also has a positive effect on prognosis (OS) in different clinical variables, such as T4 stage, N0 stage, M0 stage, female, no colon polyps present, no history of colon polyps and R0 residual tumor (P < 0.05)." (PMID 36173462, 2023). "Therefore, we hypothesized that FDX1 may regulate immune cells within the tumor microenvironment through multiple pathways, rather than specifically targeting immune cells." (PMID 35991547, 2022). "To evaluate the impact of GPRIN2 and FDX1 on the tumorigenic potential of LUAD cells in vivo, we established a subcutaneous transplantation tumor model using FDX1-overexpressing A549 cells with or without GPRIN2 knockdown in nude mice." (PMID 38802900, 2024). "We found that FDX1, LIPT1, DLAT, PDHA1, PDHB, DLST, and ATP7A were significantly differentially expressed in tumor and nontumor tissues, with the standard of p < 0.05." (PMID 36975441, 2023). "Based on the analysis of scRNA-seq, the expression of FDX1, DLD and SLC31A1 was much higher in non-tumor tissues than those in tumor tissues, consistent with our findings from a bulk sequencing analysis." (PMID 36733399, 2022). "Interestingly, FDX1 was significantly negatively correlated with the expression of many immune checkpoint genes in ACC, especially PD-1 (PDCD1), PD-L1(CD274), CTLA4 and other important immunotherapy targets, which may also be closely related to the immune escape mechanism of ACC tumor cells." (PMID 35991547, 2022). "Specifically, there was a downward trend of FDX1 and LIAS expression and an upward trend of CDKN2A expression regardless of tumor stage or histological grade." (PMID 35627236, 2022). "We found that five cuprotosis molecules, DLAT, PDHA1, FDX1, GLS and CDKN2A, were significantly different between paired tumour and adjacent non-tumour samples from the TCGA-STAD cohort, and LIAS, DLD, DLAT and MTF1 were significantly different among the four pathologic T categories 1–4." (PMID 36895378, 2023). "Notably, FDX1 knockdown failed to attenuate the synergistic inhibitory effect of DSF+Vem, while FDX1 overexpression did not enhance this combinatorial efficacy, suggesting the existence of FDX1-independent pathways mediating DSF+Vem’s anti-tumor activity." (PMID 40592836, 2025).
tumor (continued). "Importantly, the correlation of FDX1 expression and SLC31A1 expression with prognosis does not apply equally to all tumor types, and further in vivo and in vitro research is needed to separately confirm the prognostic significance of specific cuproptotic events in different types of cancer." (PMID 39062119, 2024).
cancer (104 papers, 2018 to 2025). A tumor composed of atypical neoplastic, often pleomorphic cells that invade other tissues. "This underlines the potential of FDX1 as a future target for cancer treatment and a prognostic biomarker." (PMID 38918694, 2024). "Ferredoxin 1 has been implicated in various cellular processes, including metabolism, redox regulation, and signaling pathways, which are dysregulated in cancer cells." (PMID 38802900, 2024). "FDX1, a crucial protein in cellular redox reactions and energy metabolism, has been linked to several cancers." (PMID 38802900, 2024). "Regarding the detailed genomic aberration, we found that the structural variant, amplification, and deep deletion frequency of FDX1 varied among different cancer types; amplification and deletion were the main mutation patterns in ccRCC." (PMID 36766692, 2023). "The results displayed that FDX1 expression is strongly associated with immune cells’ infiltration of the TME in multiple cancer types." (PMID 37298135, 2023). "And among the cuproptosis‐related genes we screened, FDX1 is associated with elesclomol mediated toxicity in cancer cells, where FDX1 binds directly to elesclomol, converts copper ions to cuprous ions, and releases them in mitochondria." (PMID 38131663, 2023). "It is interesting to note that we found FDX1 expression was negatively correlated with the estimated infiltration of cancer-associated fibroblasts and monocytes for the STAD." (PMID 37193786, 2023). "FDX1 exhibited a significant association with infiltrated cancer-associated fibroblasts and CD8+ T cells." (PMID 37298135, 2023). "In subsequent investigations, we intend to delve deeper into the underlying mechanism through which FDX1 promotes cancer in GBM, as well as explore potential therapeutic avenues." (PMID 38114959, 2023). "Our results showed that FDX1 expression had functions associated with cancer-associated fibroblasts, T cell follicular helper, monocyte and endothelial cells in different tumors." (PMID 37193786, 2023). "Thirdly, although we concluded that FDX1 expression was associated with prognosis of human cancers and immune cell infiltration, direct evidence concerning FDX1 playing a role in immune infiltration on prognosis is still lacking." (PMID 37193786, 2023). "In general, FDX1 expression was significantly associated with many essential pathways in human cancer formation." (PMID 37298135, 2023). "FDX1 was expressed highly in multiple types of cancer and differently linked to the survival prognosis of tumorous patients." (PMID 37298135, 2023). "Previous studies have linked FDX1 to a variety of cancers, including lung adenocarcinoma, ccRCC, hepatocellular carcinoma, and colon adenocarcinoma." (PMID 37432054, 2023). "Typically, elesclomol-mediated cancer cytotoxicity is associated with ferritin-1 (FDX1) levels and increased mitochondrial respiration rate, whilst it is also dependent on copper availability." (PMID 36158220, 2022). "Hypermethylated PDHB, LIPT1, LIAS and GLS were mainly associated with poor prognosis in cancer, whereas hypomethylated FDX1 was dominantly related to poor prognosis of LGG and ccRCC." (PMID 36581992, 2022). "We found that FDX1 was associated with infiltration levels of T cells in nine cancer types, dendritic cells in seven cancer types, monocytes-macrophages in seven cancer types and mast cells in five cancer types." (PMID 35991547, 2022). "When tumors were compared with corresponding normal tissues, FDX1 expression was reduced in various cancers, and this high expression was associated with better OS and death-specific survival in some cancer types, such as KIPC." (PMID 36061184, 2022). "Recent studies also highlight the involvement of FDX1, as well as its associated cuproptosis, in the development of various cancers." (PMID 36611966, 2022).
cancer (continued). "As shown, immune scores in 11 of the 33 cancers were significantly associated with FDX1 expression, and ESTIMATEScore scores in 14 of the 33 cancers were significantly associated with FDX1." (PMID 36061184, 2022). "Their respective relationships to FDX1 expression in various cancers were examined to investigate the link between FDX1 activity and mutations in specific cancer types." (PMID 36061184, 2022). "The FDX1 high expression is associated with better prognosis in many cancers, as revealed by pan-cancer analysis." (PMID 36105937, 2022). "FDX1 targeted by elesclomol, is implicated in cancer cell resistance to proteasome inhibitors." (PMID 40109870, 2025). "FDX1 modulates cancer cell susceptibility to cuproptosis by controlling lipoylation levels." (PMID 40897695, 2025). "Additionally, lower levels of FDX1 expression have been linked to more severe stages of tumor-node-metastasis and associated with diminished survival rates in various types of cancer." (PMID 38693584, 2024). "Furthermore, we observed that high FDX1 expression was strongly associated with age greater than 65, especially in the cancers ESCA, LUAD, OV, SKCM, and UCEC." (PMID 37298135, 2023). "Protein lipoylation was found to be closely linked with FDX1 abundance in many cancers, and cell lines with high levels of protein lipoylation were highly susceptible to cuproptosis, indicating that copper ion carrier therapy should focus on malignancies with this metabolic profile." (PMID 38023234, 2023). "Additionally, an increased FDX1 level was closely linked to excellent DFS prognostic outcomes in the cancers LIHC, THCA, and THCA." (PMID 37298135, 2023). "Mutations in the FDX1 gene were examined in all cancer types to determine whether they were associated with a poor clinical outcome." (PMID 37298135, 2023). "According to our results, FDX1 expression differed significantly between molecular and immune subtypes of most cancers, which might indicate that FDX1 is a promising diagnostic biomarker for pan-cancers and that it regulates immunity as well." (PMID 37193786, 2023). "Additionally, FDX1 has been linked to cancer progression, prognosis, and immune response across a range of cancer types." (PMID 37193786, 2023). "According to the results above, FDX1 significantly associated with cancer immunity and prognosis." (PMID 37193786, 2023). "The expression of FDX1 was associated with prognosis in patients with multiple types of cancer." (PMID 37298135, 2023). "Furthermore, proteomic analysis of 11 TCGA cancers highlighted distinctive FDX1 expression in ccRCC, revealing the underlying substantial function involved in tumourigenesis." (PMID 36186457, 2022). "Among them, the loss of FDX1, as a key gene in copper ionophores-induced death, makes cells resistant to copper-induced cell death, which is consistent with our finding that FDX1 is under expressed in many cancers." (PMID 35991547, 2022). "We found FDX1 had significant correlations with prognosis, mutation and immunity of pan-cancer." (PMID 35991547, 2022). "Moreover, FDX1 expression was positively or negatively associated with prognosis in different cancers." (PMID 36210836, 2022). "FDX1 was also associated with sensitivity to cancer chemotherapy drugs." (PMID 35991547, 2022). "Moreover, FDX1 may act as a risk factor for cancer through its regulation of DNA and RNA methylation, mismatch repair (MMR) gene expression, and tumor mutation burden (TMB)." (PMID 39702350, 2024). "Furthermore, elesclomol could be utilized to treat a variety of tumors that are particularly susceptible to the cuproptosis process, such as cancer cells with high FDX1 expression." (PMID 37056336, 2023). "Hence, researchers have explored the association between FDX1 and cancer." (PMID 36925927, 2023). "Furthermore, the FDX1 gene can increase the copper-dependent cell death caused by elesclomol, which may offer a novel approach to improving the efficacy of many cancer-targeting drugs." (PMID 36225932, 2022).
cancer (continued). "The results not only suggested that FDX1 might be a potent prognostic biomarker, which was closely associated with cancer immunomodulatory mechanisms and resistance to antitumor drugs, but also revealed its as a potential predictor of pan-cancer immunotherapy." (PMID 35991547, 2022). "The authors could show in a previous study that the iron-sulfur protein ferredoxin 1 (FDX1) is responsible for the reduction of elesclomol-bound Cu(II) to Cu(I) in mitochondria, leading to susceptibility to copper-induced cell death in certain cancer cells." (PMID 36017664, 2022). "For example, the atypical methyltransferase METTL16 promotes FDX1 accumulation through N6-methyladenosine modification of FDX1 mRNA, which ultimately leads to cancer cell copper death." (PMID 40486836, 2025). "In this review, we summarize the regulatory mechanisms governing FDX1 expression and its functional roles in cancer progression." (PMID 41853121, 2025). "Recently, several agents targeting FDX1 have exhibited promising therapeutic efficacy both in vitro and in vivo across diverse cancer models." (PMID 41853121, 2025). "Pan-cancer analysis shows that knocking down FDX1 leads to the downregulation of cuproptosis in clear cell renal tumor cells." (PMID 40897695, 2025). "In this pan-cancer analysis, we systematically profiled the expression and prognostic value of eight well-characterized cuproptosis-related genes—FDX1, LIAS, LIPT1, DLD, DLAT, PDHA1, PDHB, and SLC31A1—across 34 cancer types." (PMID 40601654, 2025). "Although the clinical application of cuproptosis-related biomarkers remains in its early stages, emerging evidence suggests that key regulators such as FDX1 hold promise as prognostic indicators and therapeutic targets in cancer." (PMID 40963614, 2025). "To further validate this finding, we measured FDX1 mRNA levels in cancer and adjacent tissues from 30 COAD patients at Nanfang Hospital using RT-qPCR." (PMID 40276654, 2025). "Transcription factors, epigenetic modifications, and non-coding RNAs (ncRNAs) contribute to the aberrant expression of FDX1 in cancer cells." (PMID 41853121, 2025). "This was further confirmed by immunohistochemical analysis, which also demonstrated low FDX1 expression in cancer tissue." (PMID 40276654, 2025). "Genes such as FDX1, CAT, CDKN2A, DLAT, LIPT1, and COMMD1, which are associated with cuproptosis, are crucial for the growth, advancement, and spread of various cancers." (PMID 40109870, 2025). "Cuproptosis-related gene ferredoxin 1 (FDX1) has been discovered to act as a suppressor, thereby suppressing some cancers’ progression." (PMID 38520567, 2025). "It functions as an electron carrier in diverse metabolic pathways and is critically involved in regulating protein lipoylation Accumulating evidence indicates that FDX1 expression is frequently dysregulated across various cancer types." (PMID 41853121, 2025). "The results showed that FDX1 expression was significantly downregulated in cancer tissues compared to adjacent tissues." (PMID 40276654, 2025). "Validating such approaches in vivo, charting upstream regulators of FDX1 and mapping crosstalk between cuproptosis and other lethal programmes remain key steps toward exploiting this copper-centred vulnerability in cancer therapy." (PMID 40778735, 2025). "Cuproptosis, a novel cell death pathway mediated by ferredoxin 1 (FDX1) and protein lipoylation, has emerged as a valuable target in cancer therapy." (PMID 40630211, 2025). "Gene deletion of FDX1 confers resistance, whereas increased gene expression of FDX1 across 724 cancer cell lines is the top correlate with increased sensitivity to treatment with elesclomol, a mitochondria-targeted copper ionophore." (PMID 39172219, 2025). "So that, FDX1 has also been discovered to own important roles to participate into various cancers’ progression through playing as a suppressor." (PMID 38520567, 2025).